BRCA1 (BRCA1 DNA repair associated)
Diseases named in the same sentence as BRCA1 in open-access papers (continued):
Sharing a sentence is not in itself a finding about the gene and the disease.
breast cancer (continued). "Unilateral breast cancer (UBC) patients harboring BRCA1/2 mutations have higher risks of developing contralateral breast cancer (CBC) after the diagnosis of the first breast cancer (1st BC) than those who do not." (PMID 34563200, 2021). "BRCA1/2 reversion mutations have been identified in smaller breast cancer cohorts with progressive disease on PARPi/platinum-based therapy, with a prevalence of ~40–50% of patients." (PMID 34959671, 2021). "The principle of inhibiting DNA repair genes has been proposed for cells that carry mutations in the breast cancer susceptibility genes BRCA1 or BRCA2 as a possible cancer drug target." (PMID 34305605, 2021). "By age 70, BRCA1 mutations increase the cumulative risk of developing breast cancer to 47–66% and ovarian cancer to 35–46%." (PMID 35008272, 2021). "It was previously known that mutations in other genes known to predispose to breast cancer, such as BRCA1/2, result in an increased risk of contralateral breast cancer." (PMID 33842116, 2021). "The BRCA1 protein is involved in DNA repair mechanisms, and it has been demonstrated that BRCA1-deficient mouse mammary tumors are enriched in CD44+/CD24−/(low) and CD133+ cells." (PMID 34359928, 2021). "The overall rate of possessing deleterious BRCA1 mutation is 12 times higher in TNBC compared to other subtypes of breast cancer." (PMID 34359598, 2021). "In 2019, 268,600 women were expected to be diagnosed with breast cancer in the U.S. The breast cancer-associated (BRCA1) gene is an important tumor suppressor that protects against genomic instability." (PMID 33441637, 2021). "In BRCA1-mutated TN breast cancer, however, some BCSCs showed relative resistance to olaparib treatment." (PMID 33672204, 2021). "It is likely that defective HR, compromised genomic integrity, repeated exposure to hormonally driven ROS, and acquisition of additional mutations, all contribute to breast cancer initiation associated with mutations or loss of function of BRCA1." (PMID 35008272, 2021). "PBSO further gives a reduction in ovarian cancer specific mortality of 95% and in breast cancer specific mortality of 42% The risk reduction in breast cancer is more pronounced for BRCA1 mutation carriers than BRCA2 mutation carriers." (PMID 33996049, 2021). "Breast cancer has become the most commonly diagnosed cancer since 2020, 0.85–3.0% of whom carry a germline pathogenic BRCA1/2 variation." (PMID 34563200, 2021). "The BGP population is ideal to study further the risk effects of breast cancer predisposing PVs such as BRCA1:c.190T>C and PALB2:c.1027C>T." (PMID 33573335, 2021). "We showed that the BRCA1:c.190T>C, is a founder variant in breast cancer families from Bergamo and has an estimated age of ~3000 years." (PMID 33573335, 2021). "RASSF1A has been demonstrated to be mutated (A133S polymorphism) in BRCA1/2 mutated gene carriers with early onset breast cancer." (PMID 34209669, 2021). "In 1990, the BRCA1 gene was linked for the first time to breast cancer using a large group of early onset breast cancer families and linkage analysis." (PMID 34573353, 2021). "By using these mutant mice and human BRCA1-deficient and proficient breast cancer tissues and cells, we tested if there exists a druggable target in BRCA1-deficient breast cancers." (PMID 33478572, 2021). "In the following, the generic term ‘preventive option or measure’ applies to all measures that can be offered to women with BRCA1/2 mutations either to reduce the risk of breast or ovarian cancer or for breast cancer screening." (PMID 34090422, 2021).
breast cancer (continued). "Approximately 3–5% of patients with breast cancer and 8–17% of patients with ovarian cancer can attribute the cancer to germline pathogenic variants in the BRCA1 and BRCA2 genes, which is called the hereditary breast-ovarian cancer (HBOC) syndrome." (PMID 34525964, 2021). "BRCA1 driven breast cancer arises from luminal progenitor cells but how BRCA1 loss-of-function affects the luminal progenitor cell state during premalignant stages of the disease is still unclear." (PMID 33686070, 2021). "The AR polymorphism characterized by longer AR-CAG repeats within the AR gene and resulting in a deficient AR activity, has been associated with an increase in breast cancer risk at an early age in patients carrying the BRCA-1 mutation." (PMID 35008851, 2021). "A total of 354 patients diagnosed with breast and ovarian cancers, including 5 male breast cancer cases, have been investigated for BRCA1/2 mutations using traditional and/or next generation sequencing technologies." (PMID 34490083, 2021). "The breast cancer susceptibility gene 1/2 (BRCA1/2) is frequently mutated in many malignant tumors, such as breast cancer and ovarian cancer." (PMID 33995041, 2021). "The most common germline mutations associated with breast cancer are in breast cancer susceptibility genes 1 and 2 (BRCA1 and BRCA2), which encode proteins responsible for double-stranded DNA repair." (PMID 34441794, 2021). "More importantly, data support that p-RPS6 confers olaparib-resistance to BRCA1-deficient breast cancer cells [see Section 4.3.4." (PMID 35008473, 2021). "CHEK2 (cell-cycle-checkpoint kinase 2) is another important gene for breast cancer susceptibility, discovered after BRCA1/2." (PMID 34771512, 2021). "Partner and Localizer of BRCA2 (PALB2) is a caretaker gene implicated in both BRCA1/2 breast cancer and Fanconi’s Anemia (FA) in the event of monoallelic and biallelic loss-of-function mutations, respectively." (PMID 34070674, 2021). "Patients who had bilateral prophylactic mastectomy had a significantly reduced risk of breast cancer development when compared to BRCA1/2-mutation carriers with two intact breasts." (PMID 35008272, 2021). "Individuals carrying a pathogenic germline variant in the breast cancer predisposition gene BRCA1 (gBRCA1+) are prone to developing breast cancer." (PMID 33898308, 2021). "Cancers of the breast, ovary, pancreas, and prostate are each associated with relatively high frequencies of germline and/or somatic mutations in BRCA1/2 resulting in HRRd." (PMID 34877933, 2021). "Heterozygous germline mutations in the BRCA1 gene predispose women to up to an 80% lifetime risk of developing breast cancer." (PMID 34377198, 2021). "The Korean National Health Insurance coverage for contralateral breast surgery in breast cancer patients with BRCA1/2 mutation carrier was initiated in March 2017 and the first patient in our cohort to receive contralateral RRM was in April 2014." (PMID 34285295, 2021). "A prospective study with 3886 breast cancer patients showed that a cumulative risk was 72% for BRCA1 and 69% for BRCA2 carriers." (PMID 33805996, 2021). "Approximately 15-20% of familial breast cancer cases are attributed to the BRCA1 or BRCA2 gene mutations." (PMID 34710987, 2021). "There have been only 6 cases of metaplastic breast carcinoma with germline BRCA1 mutations including our case." (PMID 33407746, 2021). "The estimated cumulative risk of breast carcinoma for male BRCA1 mutation carriers at age 70 years was 1.2% and for BRCA2 mutation carriers, 6.8%." (PMID 34356066, 2021).
breast cancer (continued). "This study was conducted to elucidate the clinicopathological characteristics and the prognostic relevance of BRCA1/2 mutations on long-term survival outcome in Egyptian female breast cancer patients." (PMID 34206661, 2021). "T he lifetime risk of ovarian and breast cancer (BC) in women with pathogenic variants in BRCA1 and BRCA2 gene is 72% and 69%, 44% and 17%, respectively." (PMID 34627117, 2021). "Around 5% of all breast carcinoma patients and 12 to 18% of breast cancer in young patients are associated with Hereditary Breast and Ovarian Cancer Syndrome, which are caused by BRCA1 or BRCA2 mutations." (PMID 34944094, 2021). "Cancer survivors harboring inherited pathogenic variants in the breast cancer (BC) susceptibility genes BRCA1 or BRCA2 are at increased risk of ovarian cancer (OC) and also of contralateral BC." (PMID 33466630, 2021). "For example, in general, basal-like breast carcinoma has been known to harbor mutations involving BRCA1, CCNE1, AKT3, or MYC; however, these genes were largely wild type, and NOTCH1 mutations were relatively common in our SeC-EOs." (PMID 34638295, 2021). "The most frequent predisposing genetic alterations are in the BRCA1 and BRCA2 genes, with a cumulative lifetime risk for breast cancer (BC) of 72% and 69% for carriers of pathogenic variants in BRCA1 and BRCA2, respectively." (PMID 34503502, 2021). "In Cyprus, approximately 9% of triple-negative (estrogen receptor-negative, progesterone receptor-negative, and human epidermal growth factor receptor 2-negative) breast cancer (TNBC) patients are positive for germline pathogenic variants (PVs) in BRCA1/2." (PMID 33120919, 2020). "To investigate this possibility, we analyzed expression data from PDX breast cancer models originating from BRCA1 mutation carriers whose sensitivity to olaparib had also been characterized." (PMID 32400970, 2020). "Perhaps the best example of this is the well-reported link between BRCA1/2 mutations and sensitivity to cisplatin in breast cancer." (PMID 32457904, 2020). "Risk estimates in Ashkenazi Jewish breast cancer patients with BRCA1/2 mutations suggested that engaging in physical exercise and maintaining healthy body weight at adolescence significantly delayed BRCA1/2-associated breast cancer onset." (PMID 33212987, 2020). "This meaningful attenuation must be considered when using population-based PRS to predict breast cancer risk for BRCA1/2 carriers and should be incorporated into breast cancer risk prediction models." (PMID 32665703, 2020). "The most common mutations in the BRCA1 gene include S1613G on exon 16 and P871L on exon 11 in combination with E1038G, which were found in breast cancer families in India, Greece, Turkey, and Italy." (PMID 32356124, 2020). "Pathogenic germline mutations in BRCA1 are responsible for approximately 20% of familial breast cancers." (PMID 33162807, 2020). "Intriguingly, in contrast to BRCA2, BRCA1 mutations are thought to contribute to more cases of early onset breast cancer." (PMID 33505905, 2020). "The unadjusted odds of breast cancer being MF/MC in BRCA2 mutation carriers were 3.2 times greater than in BRCA1 mutation carriers (CI: 1.57–6.57, p = 0.001)." (PMID 32022473, 2020). "Pathogenic variants in the tumor suppressor breast cancer genes BRCA1 and BRCA2 increase the risk of female breast and ovarian cancers." (PMID 32518611, 2020). "In our study, from this thought, we analyzed the difference in genetic expression profiles and interaction networks between mutant and wild-type by selecting transcriptome data from breast cancer patients with BRCA1/2 mutations." (PMID 31998560, 2020). "Breast cancer susceptibility gene-1 (BRCA1) has been recognized as one of the risk factors for breast cancer occurrence and development." (PMID 33817238, 2020). "Inherited mutations in the BRCA1 gene predispose carriers to early-onset tumourigenesis and an up to 87% cumulative lifetime risk of developing breast cancer and/or ovarian cancer." (PMID 32591500, 2020).
breast cancer (continued). "Genetic predisposition reportedly accounts for 5 to 10% of breast cancers, notably through alterations of the BRCA1 and BRCA2 genes." (PMID 32650744, 2020). "For example, breast cancers diagnosed in BRCA1-mutation carriers are frequently of a high Nottingham grade and display medullary morphology and a triple-negative and/or a basal-like immunophenotype." (PMID 33117676, 2020). "The most common causes of HBOC are mutations in the breast cancer susceptibility 1 and 2 genes (BRCA1 and BRCA2, respectively)." (PMID 36312308, 2020). "For breast cancer and ovarian cancer patients, BRCA1 mutations also increased chemosensitivity and/or radiosensitivity." (PMID 32685473, 2020). "First, it was shown that AKT inhibition using the investigational drug MK-2206 suppresses the initiation and progression of BRCA1-associated mammary tumors." (PMID 33424604, 2020). "We analyzed the BRCA1 pathogenic variant, p.Ile1845fs, with breast cancer risk in 23,481 invasive breast cancer cases (46.24 ± 20.11 years) and age-matched 6489 controls (47.33 ± 13.46 years)." (PMID 31908633, 2020). "In the adjuvant setting, the results from the OlympiA phase III study, evaluating adjuvant olaparib in HER2-negative early breast cancer and germline BRCA1/2 mutations, are eagerly awaited." (PMID 32471249, 2020). "TNBC tumors are associated with pathogenic variants in the BRCA1 breast cancer susceptibility gene, with 7–20% of diagnosed patients harboring pathogenic germline or somatic variants." (PMID 32719340, 2020). "Rhiem further observes that patients diagnosed with breast cancer at age <40 years had a cumulative risk 25 years from primary diagnosis of 55.1% and 38.4% for BRCA1 and BRCA2-positive family history, respectively." (PMID 31935898, 2020). "In less than 5% of cases, breast cancers (BC) are associated with germline mutations in breast cancer 1 (BRCA1) or breast cancer 2 (BRCA2) (gBRCA1/2m) genes." (PMID 32471249, 2020). "In our SBBC patients, bilateral ER-negative status, young age and a family history of breast cancer were associated with a high risk of BRCA1/2 mutation." (PMID 32117708, 2020). "Although mosaicism for BRCA1/2 mutations seems to be rare, this and previous work demonstrates that low-level mosaic mutations can contribute to the etiology of breast cancer susceptibility." (PMID 32468491, 2020). "High-penetrance genes, such as BRCA1 and 2, are one of the strongest risk factors for breast cancer incidence, and screening of women over 50 and those at high risk results in a 30 percent reduction in cancer mortality." (PMID 33255309, 2020). "Our group recently published our first experience with BRCA1/2 research among 100 high-risk patients with breast cancer in Jordan." (PMID 32083950, 2020). "Currently, PARP inhibitors are under clinical trials for BRCA1/BRCA2-deficient breast cancer and ovarian cancer by the approach of synthetic lethal." (PMID 32711558, 2020). "Because breast cancer 1 (Brca1) and breast cancer 2 (Brca2) associates with ovarian aging, we prospectively compared serum AMH concentrations in wt mice, Brca1+/- mice, Brca2+/- mice and Pol β+/- mice at the same age." (PMID 33223510, 2020). "Mutation in BRCA1 gene is considered as the main cause of hereditary breast cancer, and it is responsible for 40–45% of total hereditary breast cancer development." (PMID 33013205, 2020). "BRCA1 mutation breast cancers are predominantly triple negative/basal-like, which means these cancers lack the expression of human epidermal growth factor receptor 2, estrogen receptor (ER), and progesterone receptor (PR)." (PMID 33299637, 2020). "Variants more prevalent in the French-Canadian population have been identified in established breast cancer predisposition genes BRCA1, BRCA2, and PALB27–14." (PMID 32300229, 2020). "Two variants (BRCA1 c.4460A>G and c.824G>A) were recurrent in discovery stage in two patients with breast cancer and/or ovarian cancer family history." (PMID 32879886, 2020).
breast cancer (continued). "Gene expression profiles from The Cancer Genome Atlas (TCGA) database were downloaded and combined with cBioPortal website to identify exact breast cancer patients with BRCA1/2 mutations." (PMID 31998560, 2020). "The present investigation showed that variations in BRCA1 made substantial contribution in causing hereditary/early-onset breast cancer in Pakistani women." (PMID 32063924, 2020). "We have studied survival associations of genetic variants in two etiologically unique groups of breast cancer patients, the carriers of germline pathogenic variants in BRCA1 or BRCA2 genes." (PMID 32964118, 2020). "Deleterious variants in BRCA1/2 confer a strong predisposition to breast cancer, and increase the relative risk to carriers by about 10- to 20-fold, as compared to that for the general population." (PMID 32300589, 2020). "To assess the association between BRCA1 methylation and response to cytotoxic chemotherapy, we obtained information on chemotherapy and used time to patient death (breast cancer–specific survival) as a proxy for treatment response." (PMID 32175521, 2020). "Although approximately 12% of women in general population develop breast cancer all through their life, 72% of women with pathogenic BRCA1 mutation and 69% of women with pathogenic BRCA2 mutation are diagnosed with breast cancer at a stage of life." (PMID 33488844, 2020). "The fourth BRCA1 pathogenic variant c.1016dupA (p.Val340fs) was detected in a patient suffering from luminal breast cancer." (PMID 32778078, 2020). "In women with BRCA1 mutations, the risk of developing breast cancer by the age of 70 years is 57% and that of ovarian cancer is 40%." (PMID 32722046, 2020). "The odds of a woman who had developed breast cancer exhibiting MF/MC disease were over three times greater if she had a BRCA2 mutation compared to a BRCA1 mutation." (PMID 32022473, 2020). "A study conducted in North India, shows early onset of breast cancer with positive family history was associated with BRCA1 gene mutation." (PMID 32856854, 2020). "A woman’s lifetime risk of developing breast cancer is greatly increased when she inherits a BRCA1 or BRCA2 gene mutation." (PMID 31832891, 2020). "Altogether, these human data strongly support the idea that the RANKL/RANK/OPG axis is intimately involved in the tumorigenesis of BRCA1/2 mutation-driven breast cancer." (PMID 32850393, 2020). "Similar results were also observed with clinical benefit of olaparib in BRCA2 mutated pancreatic cancer and in BRCA1/2 mutated breast cancer." (PMID 32778095, 2020). "One of the well-studied genes that has been associated with breast cancer,BRCA1 (MIM 113705), is located at the chromosomal position17q21 and contains 24 exons (Miki etal., 1994)." (PMID 32453341, 2020). "First, we found 10 cases harboring germline predisposing variants in BRCA1/2 genes, the prevalence of which (5.5%, 10/183) is slightly higher than those of human cancers (2.9–3.0%), measured in a meta-analysis of unselected breast cancer patients." (PMID 32680987, 2020). "Women carrying germline mutations in BRCA1 or BRCA2 are at high risk of developing breast cancer and ovarian cancer." (PMID 31948486, 2020). "Of the 211 BRCA1/2 carriers diagnosed with breast cancer (with MF/MC information available) in Northern Ireland between 1994 and 2017, 90 (42.7%) women had a BRCA1 mutation and 121 (57.3%) a BRCA2 mutation." (PMID 32022473, 2020). "PRO data is incredibly valuable to get insight into long-term HRQoL and can be used as a guide for BRCA1/2 mutation carriers in their decision-making process in regard to their breast cancer risk management." (PMID 31832891, 2020). "We aimed to accurately evaluate the prevalence of case-only variants in BRCA1/2 not only in breast cancer cases but also for other cancer types (e.g., cervical cancer, colorectal cancer, and hepatocellular carcinoma)." (PMID 32879886, 2020).